INS (insulin)
Diseases named in the same sentence as INS in open-access papers (continued):
Sharing a sentence is not in itself a finding about the gene and the disease.
steatosis (continued). "In summary, the present study provided evidence to support the potential therapeutic effects of BBR on reducing liver inflammation and steatosis while improving systemic insulin sensitivity and glucose homeostasis." (PMID 26936230, 2016). "Early stage steatosis arose even when simulating a healthy (moderate intake) diet in an insulin resistant individual." (PMID 27632189, 2016). "Increasing evidence shows that hepatic ER stress is associated with the pathogenesis of several liver diseases and metabolic disorders, including steatosis and hepatic insulin resistance." (PMID 26805878, 2016). "In the liver, a large reduction in the size of lipid droplets and a reduction in OS were observed following Ex‐4 treatment, suggesting elevated lipolysis, reduced steatosis, and improved insulin sensitivity." (PMID 27511983, 2016). "Pioglitazone group had a significant improvement in ALT, insulin sensitivity as well as steatosis, ballooning, and inflammation." (PMID 27006654, 2016). "An increasing body of evidence supports the notion that hepatic IR signalling is required for the development of steatosis in an insulin-resistant state." (PMID 27708333, 2016). "Since we found impaired systemic insulin sensitivity in female Gnmt−/− mice, we subsequently evaluated the hepatic steatosis and de novo lipogenesis in these mice." (PMID 27716281, 2016). "Taken together, these data suggest that chronic insulin exposure drives a steatosis-like LB accumulation in mast cells, with marked and selective effects on their pro-inflammatory outputs." (PMID 26263026, 2015). "We have previously shown in vitro that insulin-influenced lipogenic pathways induce LB biogenesis in mast cells, with their numbers attaining steatosis-like levels." (PMID 26263026, 2015). "Regnell and Lernmark also emphasize that insulin plays an important role in the genesis of steatosis in rodent hepatocytes because it modulates the flow of FFAs that is transported by protein pathways mediated by 2 and 5 FATPs (fatty acid transport proteins)." (PMID 25789328, 2015). "It is also possible that inhibition of the MGAT2 isozyme in the liver will improve steatosis by attenuating fat accumulation and insulin resistance." (PMID 28943619, 2015). "The P-M1/M2 ratio positively correlated with steatosis grade (r = 0.39; p = 0.02) and with fasting insulin (r = 0.47; p = 0.003)." (PMID 26599575, 2015). "The P-M1/M2 ratio positively correlated with steatosis grade (r = 0.39, p = 0.02) and insulin (r = 0.47, p = 0.003)." (PMID 26599575, 2015). "Many studies have reported that substitutions in the HCV core region results in enhanced insulin resistance, steatosis, oxidative stress and HCC." (PMID 25270660, 2014). "These increases were paralleled by increases in random blood glucose and insulin levels and enhancement of microvesicular steatosis and macrophage accumulation in adipose tissue." (PMID 24398136, 2014). "This is consistent with another in vitro study demonstrating that the addition of a monounsaturated FA attenuates hepatocyte apoptosis and insulin resistance caused by exposure to a SFA, despite causing increased steatosis." (PMID 24830559, 2014). "In good agreement with this assumption, another study demonstrated that HuApoC-III mice fed a high fat diet become insulin-resistant and develop steatosis and NASH." (PMID 25047818, 2014). "Enhancers of autophagy such as carbamazepine and rapamycin have been recently tested in HFD-obese mice and both had protective effects in reducing steatosis and in improving insulin sensitivity." (PMID 25295245, 2014). "HCV infection often leads to liver fibrosis and cirrhosis, various metabolic alterations including steatosis, insulin and interferon resistance or iron overload, and development of hepatocellular carcinoma or non-Hodgkin lymphoma." (PMID 23358390, 2013). "BMI, γ-GT, FPG, insulin, and insulin sensitivity estimated by the HOMA index were significantly higher in patients with steatosis." (PMID 23914225, 2013).
steatosis (continued). "Molecular studies in the NAFLD support a key role for PTEN in hepatic insulin sensitivity and the development of steatosis, steatohepatitis, and fibrosis." (PMID 23431468, 2013). "Intensive insulin therapy in type 2 diabetic patients with NAFLD/NASH appears to significantly decrease on steatosis." (PMID 23653642, 2013). "Liver specific deletion of the tumor suppressor phosphatase and tensin homologue deleted on chromosome 10 (PTEN) induces steatosis and hypersensitivity to insulin." (PMID 23691291, 2013). "Body mass index, γ-GT, FPG, insulin, and insulin sensitivity estimated by the HOMA index were significantly higher in patients with steatosis." (PMID 23914225, 2013). "A recent study has shown that reducing ADRP and TIP47 in the liver via antisense oligonucleotide treatment attenuated steatosis and improved insulin sensitivity and glucose metabolism in C57BL/6J mice fed with high-fat diet." (PMID 24307947, 2013). "HFD significantly increased total fat and triacylglyceride contents with macrovesicular steatosis, concomitantly with higher fasting serum glucose and insulin levels, HOMA, and serum TNF-α, IL-1β, and IL-6." (PMID 23082120, 2012). "The insulin sensitizing action of leptin and adiponectin normalizes insulin levels which further helps in preventing CLA-induced steatosis." (PMID 21869929, 2012). "Nonetheless we still had successful transplantation due to several results, namely, steatosis and liver weights were much improved, plasma glucose and NEFAs were improved, as were insulin, cholesterol and triglycerides." (PMID 22792234, 2012). "The pioglitazone-treated group showed an improvement in ALT (by 50%), steatosis (by 54%), insulin sensitivity (by 48%), liver inflammation, and ballooning necrosis but not fibrosis." (PMID 22194737, 2012). "Fish oil, a source of PUFA has been shown to ameliorate CLA-induced steatosis by increasing leptin and adiponectin levels and decreasing plasma insulin." (PMID 21869929, 2012). "The ribosomal protein PRAS40, abundant in steatosis patients has been identified as a crucial regulator of insulin signaling and also as mediator of AKT signals to mTOR." (PMID 22969728, 2012). "The mechanism of free fatty acid induced steatosis was studied in cell culture with mouse liver cells under different insulin concentrations, pharmacological phosphoinositol-3-kinase (PI3K) inhibition and siRNA targeted gene knock-down." (PMID 22745692, 2012). "Many authors have observed and also correlated amino acid substitution in Core in HCV infected patient's samples with steatosis, interferon response, insulin resistance and oxidative stress." (PMID 21457561, 2011). "In contrast, Timp3 deficient animals fed a high fat diet for five months experienced increased TACE activity, became glucose-intolerant and insulin-resistant and developed severe macrovesicular steatosis compared to wild-type mice." (PMID 21980496, 2011). "The primary endpoints were measurements in SVR, liver enzyme, cholesterol, triglyceride, CRP, glucose, and insulin levels; and Homa-IR, fibrosis, and steatosis scores." (PMID 22087124, 2011). "After two weeks, Marimastat-treated animals significantly improved surrogate markers for insulin sensitivity and liver histology, and experienced a 66% decrease in steatosis (P = 0.010)." (PMID 21980496, 2011). "We demonstrate that Marimastat treatment improves surrogate markers for insulin sensitivity and reverses steatosis in both animal models by interfering, in all likelihood, with TACE activation and signaling." (PMID 21980496, 2011).
steatosis (continued). "Inhibiting serine palmitoyltransferase, the initial rate-limiting step in sphingolipid synthesis, with myriocin lowered ceramide levels, improved glucose tolerance, increased insulin sensitivity, and decreased hepatic steatosis in diabetic rodent models." (PMID 20574539, 2010). "Conversely, knock-out of Ccl2 or its receptor Ccr2, improves insulin sensitivity and prevents steatosis." (PMID 19513120, 2009). "Infliximab (anti-TNF-α) reverses the steatosis and the expression of the proinflammatory markers (TNF-α, IL6, IL-1B) and improves insulin signal trasduction in a model of steatosis in rats." (PMID 18782455, 2008). "However, the reduction of PLIN3 has been shown to ameliorate steatosis and improve insulin sensitivity in models of MAFLD." (PMID 41559682, 2026). "Huh-7 is distinguished by its accessibility and suitability for studying steatosis, lipotoxicity, insulin resistance, and paracrine mechanisms of fibrogenesis; however, its use is limited by its tumor origin, impaired carbohydrate metabolism, and low activity of xenobiotic-metabolizing enzymes." (PMID 42196430, 2026). "First, ALT serves as a well-established biomarker of hepatocellular injury and inflammation; its elevation often precedes the onset of steatosis and reflects enhanced hepatic de novo lipogenesis, which is frequently driven by excessive carbohydrate intake and insulin resistance." (PMID 41426575, 2025). "A reduction in their adipose resistance index may lead to diminished lean organ steatosis and reduced appetite due to a decrease in orexigenic signals, mainly free cortisol and insulin." (PMID 41122708, 2025). "Improved insulin sensitivity further alleviates steatosis and oxidative stress." (PMID 41031363, 2025). "Higher MIND scores were associated with reduced steatosis as measured by HSI and CAP, lower fibrosis indicated by the FIB-4 index, improved insulin sensitivity reflected by lower HOMA-IR values, decreased liver enzyme levels, and a more favorable lipid profile." (PMID 40927568, 2025). "The meta-analysis encompassing 25 controlled trials found that flavonoid treatment could significantly reduce ALT, AST, ALP, BMI, TC, TG, FBS, insulin levels, Steatosis score and there was significant increase in QUICKI." (PMID 41031363, 2025). "Importantly, SHTG often coexists with metabolic dysfunction-associated steatotic liver disease (MASLD), reflecting a bidirectional relationship between hepatic insulin resistance, steatosis, and impaired clearance of triglyceride-rich lipoproteins." (PMID 41300829, 2025). "Moreover, patients exhibiting lower grades of steatosis presented with elevated circulating levels of adiponectin, a hormone known for its anti-inflammatory and insulin-sensitizing properties." (PMID 41010458, 2025). "Oral signal centered on Aggregatibacter actinomycetemcomitans: higher anti-Aa IgG, as well as weakly higher anti-Fusubacterium nucleatum, were linked to greater visceral/total adiposity, higher fasting insulin and HOMA-IR, and a lower CT liver–spleen ratio (more steatosis)." (PMID 41294484, 2025). "The improved insulin sensitivity, combined with increased insulin secretion, prevents peripheral lipolysis, reduces free fatty acids in circulation and the liver, and decreases triglyceride synthesis and steatosis in hepatocytes." (PMID 41322896, 2025). "However, PI3KγNest mice showed reduced adiposity, steatosis, and improved insulin sensitivity also compared to Nestin-CRE mice, indicating that the metabolic phenotype of PI3KγNest mice depends on PI3Kγ deletion." (PMID 39811649, 2025). "The ketogenic diet (KD), a high-fat, low-carbohydrate diet, induces hepatic insulin resistance and steatosis in animal models through unknown mechanisms." (PMID 40864559, 2025). "Furthermore, enhanced lipid build-up, vacuolization and macrovesicular steatosis are the cardinal features displayed by the liver under high-fat diet-induced insulin-resistant conditions." (PMID 38745315, 2024).
steatosis (continued). "Higher fasting insulin levels and higher BMI were found in patients with steatosis." (PMID 38537007, 2024). "However, in mice models, it has been reported that an excess exposition of dietary fat induces hepatic insulin resistance and steatosis." (PMID 38577162, 2024). "Conversely, reducing HCT to its physiological level was anticipated to rescue beta-cell function, insulin sensitivity, and overall glucose homeostasis by enhancing insulin secretion and preventing the induction of gluconeogenesis and steatosis in the liver model." (PMID 39025915, 2024). "Surprisingly, intake of 67 % High BCAA ameliorates NAFLD by inhibiting tryptophan-ILA-AHR and activating MAPK9 ubiquitination, inhibiting DNL and steatosis, increasing hepatic insulin sensitivity, promoting ketogenesis and fatty acid oxidation via activating PPAR-RXR and pexophagy." (PMID 39426289, 2024). "Hence, despite the beneficial effect shown in the present work, previous studies by our group demonstrated that ACE2 deletion leads to endothelial dysfunction and vascular oxidative stress, as well as steatosis and impaired insulin signaling in the liver." (PMID 39273464, 2024). "Interestingly, these alterations of adipose tissue phenotype were correlated with a lower liver mass, smaller steatosis and maintained insulin sensitivity of the organ." (PMID 39404367, 2024). "We also observed that in rats fed a high-fat diet, the hepatic expression was reduced, which may be associated with the increased glucose circulation concentration, thus worsening insulin sensitivity and favoring steatosis deterioration." (PMID 38794739, 2024). "18-HEPE and PDX in association with improved inflammation and steatosis status but not improved insulin sensitivity." (PMID 36778746, 2023). "Results of some animal studies suggest that hepatic insulin resistance and steatosis may result from an increase in hepatic diacylglycerol accumulation, and an associated protein kinase C activation leading to alterations of insulin-mediated Akt activation." (PMID 37596353, 2023). "In one case, steatosis resolved after graft failure, supporting a paracrine insulin mechanism." (PMID 37711891, 2023). "Taken together, these findings suggested that changes in insulin signaling molecules were associated with hepatic changes in simple steatosis rather than NAFLD progression." (PMID 37047411, 2023). "Lysophosphatidylcholines (lyso-PCs) are phospholipids with anti-inflammatory and insulin-sensitizing effects; lower levels of lyso-PCs are observed in obesity, and when compared to their obese counterparts, lean patients with steatosis showed a higher level of lysine concentration." (PMID 37375618, 2023). "In agreement, GLP1R agonists have been reported to reduce hepatocarcinogenesis in non-obese chemical carcinogen-induced mouse models of HCC, perhaps by limiting liver pro-tumorigenic metabolic factors such as hepatic insulin resistance, steatosis and inflammation." (PMID 38155202, 2023). "Patients with steatosis, regardless of the BMI, have an associated genetic predisposition, increased visceral adiposity, insulin resistance, poor eating habits, and little exercise." (PMID 37375618, 2023). "The increased body weight/adiposity and systemic insulin resistance in HFD-fed Alb-Cre Nox4fl/fl mice may have contributed to the increased steatosis by promoting the flux of lipids from adipose tissue." (PMID 38060313, 2023). "On the other hand, elevated DKK1 expression activates the JNK signaling pathway, which further inhibits AKT-FOXO1 phosphorylation cascades, promoting insulin resistance and glucose metabolism disturbances, thereby accelerating excessive lipid accumulation and steatosis." (PMID 36410795, 2023). "PPARγ agonists are insulin-sensitizing agents; however, the overactivation of PPARγ may induce weight gain and steatosis in patients and animals." (PMID 35873595, 2022).
steatosis (continued). "Moreover, overexpression of Mogat1 promoted the TG synthesis, while knockdown of liver Mogat1 decreased body weight, improved insulin sensitivity, and alleviated hepatic lipid accumulation and steatosis in HFD-induced and genetic obese mice." (PMID 36012616, 2022). "We next assessed insulin significance during possible TM4SF5-dependent steatosis via NCFD." (PMID 35123128, 2022). "Multivariate regression showed that waist-to-hip ratio, fibroblast growth factor (FGF) 21, FGF19, adiponectin-to-leptin ratio, insulin, albumin, triglyceride, total-cholesterol, and alanine-aminotransferase were independent predictors of steatosis (rank-ordered by Wald)." (PMID 35663311, 2022). "Interaction of FGF21/SHBG/RBP4 and adiponectin could reduce fatty acid synthesis and enhance FAO via activation of AMPK, and then resist steatosis and increase insulin sensitivity, but also could activate PPARα and inhibit NF-kB pathway." (PMID 36267567, 2022). "On the contrary, adiponectin, an adipocyte-secreted hormone inversely correlated with obesity and with determining roles in insulin sensitivity, glucose levels, and lipid metabolism, has been reported to protect the liver from steatosis, inflammation, and fibrosis." (PMID 36009862, 2022). "The elevated serum VD level might alleviate inflammation/steatosis of the liver and improve insulin sensitivity by activating liver macrophage vitamin D receptors (VDR)." (PMID 36172527, 2022). "The steatosis might, in part, be explained by enhanced lipolysis, also given the reduced insulin secretion." (PMID 36481684, 2022). "COM may augment the synthesis of S1P in the hepatocytes, which may constitute the protective mechanism against inflammation and progression of the hepatic insulin resistance that may occur at the beginning of the steatosis development." (PMID 33673122, 2021). "As a result, PTP1B inactivation by H2O2 improved insulin signaling and protected from steatosis." (PMID 33276146, 2021). "JNK potentially impairs proximal insulin signaling directly, whereas transcription of XBP1s could promote hepatic steatosis, which may further drive hepatic insulin resistance via DAG/PKCε signaling." (PMID 35155528, 2021). "Additionally, compared to male mice, aged female mice, had better insulin sensitivity and reduced steatosis after obesogenic diet feeding." (PMID 34099626, 2021). "It has been observed that the hepatocyte-specific deletion of IFNαR1 worsened steatosis and inflammation but not insulin resistance in mice fed with a choline-deficient diet or HFD." (PMID 33924165, 2021). "Further, we show that PLIN5 function in BAT influences systemic glucose metabolism via secondary effects on iWAT (adipocyte size, thermogenic gene expression, inflammatory gene expression, insulin signaling, and lipolysis) and liver (steatosis, insulin signaling)." (PMID 34083525, 2021). "In support of this, a study observed that mice fed with KD sustained unimpaired insulin-induced hepatic Akt phosphorylation and whole-body insulin responsiveness but ultimately developed hepatic endoplasmic reticulum stress, steatosis, cellular injury, and macrophage accumulation." (PMID 34795641, 2021). "The consumption of the prebiotic resulted in the transportation of substantial acetate content to the liver via the portal vein, in which the SFCA activates hepatic FFAR2 signalling, thereby likely modulating hepatic insulin signalling to protect against steatosis." (PMID 34530928, 2021). "The minimum concentrations of glucose, fructose, insulin and fatty acids that resulted in robust induction of steatosis without loss of viability were identified." (PMID 34959755, 2021). "In hepatic IR, the clearance of glucose in the liver is impaired and is later compensated for by an increase in insulin production by the pancreas; however, this leads to not only hyperinsulinemia but also an overstimulation of lipogenesis, ultimately resulting in steatosis." (PMID 34680608, 2021).